LY6G6D (lymphocyte antigen 6 family member G6D)
Synonyms: C6orf23; G6D; MEGT1; NG25; Ly6-D
Tractability: Antibody: UniProt places it where antibodies can reach, with high confidence; its Gene Ontology location is reachable by antibodies, with high confidence; UniProt predicts a signal peptide or a membrane-spanning region.
Gene: Protein-coding gene on chromosome 6 (31,715,348 to 31,717,919, forward strand). Ensembl gene ENSG00000244355.
Subcellular location: Cell membrane; Cell projection, filopodium
Pathways (Reactome):
Metabolism of proteins: Post-translational modification: synthesis of GPI-anchored proteins
Gene Ontology:
Molecular function: identical protein binding; protein binding; acetylcholine receptor inhibitor activity
Biological process: acetylcholine receptor signaling pathway
Cellular component: external side of plasma membrane; protein-containing complex; extracellular region; plasma membrane; filopodium; synapse
Genetic constraint (gnomAD): Loss-of-function variants: 4 observed, 7.73 expected, observed/expected ratio (o/e) 0.52, 90% interval 0.25 to 1.18. That is too few expected variants to judge how well the gene tolerates losing a copy. Missense variants: 70 observed, 75.5 expected, observed/expected ratio (o/e) 0.93, 90% interval 0.76 to 1.13. Synonymous variants: 28 observed, 30.14 expected, observed/expected ratio (o/e) 0.93, 90% interval 0.69 to 1.27.
Homologues: Orthologues: chimpanzee LY6G6F (86% identical), macaque g6g-ly6g6d (86% identical), rabbit LY6G6D (76% identical), pig LY6G6D (71% identical), dog LY6G6D (67% identical), guinea pig LY6G6D (67% identical), mouse Ly6g6d (63% identical), rat Ly6g6d (57% identical). Paralogues in human: LY6G6F (11% identical).
Diseases named in the same sentence as LY6G6D in open-access papers:
LY6G6D is named in the same sentence as 19 diseases in open-access papers, as found by Europe PMC text mining. Sharing a sentence is not in itself a finding about the gene and the disease. The quoted sentences say what the papers report.
colorectal cancer (7 papers, 2019 to 2024). A primary or metastatic malignant neoplasm that affects the colon or rectum. "The Lymphocyte Antigen 6 Family Member G6D (LY6G6D) gene codes for a protein that is mainly present on the surface of colorectal cancer (CRC) cells." (PMID 38791382, 2024). "In this context, we have recently identified lymphocyte antigen 6, member of the G6D family (LY6G6D), as a tissue-specific antigen that is unique to colorectal cancer and has minimal or relatively low expression in normal colorectal mucosa." (PMID 35953834, 2022). "Clone 10C1 was selected to study the prevalence of LY6G6D in colorectal cancer (CRC), as its staining was blocked with 50x recombinant LY6G6D protein, confirming its specificity for LY6G6D." (PMID 36159851, 2022). "The expression of LY6G6D was five times higher in colorectal carcinomas than in the corresponding normal mucosa." (PMID 35953834, 2022). "In all data sets, LY6G6D was highly expressed in colorectal cancer compared to normal tissues, whereas FUT4 expression levels, tended to be significantly higher in CRC than in normal mucosa in two out of three databases." (PMID 30670049, 2019). "LY6G6D can lead to the progression of colorectal cancer and colon adenocarcinoma." (PMID 35186021, 2022). "To decipher the variations of LY6G6D expression in different histological subtypes of colorectal carcinoma, we examined the gene expression profiles in the TCGA database, which includes samples of colon adenocarcinoma (COAD, N = 478) and rectal adenocarcinoma (READ, N = 166), respectively." (PMID 35953834, 2022). "By examining gene expression profiles in serrated colorectal carcinomas, we recapitulated the results obtained in TCGA and found that mucinous subtypes had lower expression of LY6G6D compared with non-mucinous colorectal carcinomas, even within specific histological variants." (PMID 35953834, 2022). "Overall, we evaluated the immunohistochemical expression of LY6G6D in (n = 334) colorectal cancer tissues consisting of 51 (15%) mucinous and 283 (85%) non-mucinous adenocarcinomas, respectively." (PMID 35953834, 2022).
colon carcinoma (6 papers, 2016 to 2023). "In tumor tissues, the highest expression of LY6G6D was in colon carcinoma, and LY6G6D was significantly overexpressed only in colon tumor tissues." (PMID 35953834, 2022). "A subcluster of genes encoding proteases (PRSS33), protease inhibitors (R3HDML), and cytoskeletal factors (TNNC2) was overexpressed only in colon tumor tissues and resembled the expression pattern of LY6G6D." (PMID 35953834, 2022). "In line with this, coexpression of LY6G6D and CD15 increases the risk of disease progression in response to therapy, suggesting that both MAPK and Stat5 pathways likely foster colon cancer progression in concert." (PMID 30670049, 2019). "Similarly, the LY6G6D, marker gene of cluster 1, was up-regulated in both colon cancer and rectal cancer tissues." (PMID 36816947, 2023). "We here provide evidence that LY6G6D and CD15 promote chemo-immune-resistance in immunologically compromised colon cancers and can be used as biomarkers to decide patients treatment." (PMID 30670049, 2019). "Protein expression generally did not correspond to mRNA expression for the remaining markers, i.e. GRM8, LY6G6D/F, SLCO1B3 and TLR4, indicating that protein levels for these markers are likely regulated after translation in this set of colon cancer cells." (PMID 26894861, 2016). "A recent study evaluated LY6G6D and CD15 as predictive biomarkers for the response to JAK- and MAPK-directed therapies and found that these two biomarkers promote chemo-immune-resistance in immunologically compromised colon cancers and can be used as biomarkers to decide patients treatments." (PMID 38304289, 2023).
colon adenocarcinoma (3 papers, 2022 to 2024). "We found that the expression levels of LY6G6D were significantly lower in mucinous adenocarcinomas (MAD) than in classic colon adenocarcinomas (CAD), regardless of anatomic location." (PMID 35953834, 2022).
adenoma (1 paper, 2022). A neoplasm arising from the epithelium. "Here, we show that expression of LY6G6D is activated following the classical adenoma-carcinoma sequence but downregulated in mucinous CRC, regardless of primary tumor site." (PMID 35953834, 2022). "In this study, we show that the LY6G6D gene is characterized by relatively high basal DNA methylation in both the promoter and gene body regions, and its expression is activated by DNA hypomethylation through the classical adenoma-carcinoma sequence." (PMID 35953834, 2022). "Interestingly, a clear overlap was observed between classical adenocarcinoma and tubular/villous adenoma, suggesting that upregulation of LY6G6D occurred early in adenoma and persisted after malignant transformation following the well-defined sequence from adenona to adenocarcinoma." (PMID 35953834, 2022). "To better understand whether epigenetic changes in LY6G6D play a role in CRC carcinogenesis, we analyzed DNA methylation changes at TSS and in the gene body in an independent data set that included normal colonic mucosa and low- and high-grade adenomas." (PMID 35953834, 2022).
monocytopenia (1 paper, 2019). "Consistent with this, LY6G6D expression is also enhanced in rare immune diseases, such as the autosomic dominant monocytopenia, characterized by systemic immune suppression." (PMID 30670049, 2019).
mucinous carcinomas (1 paper, 2022). "In contrast, we found that strong/intense membranous/cytoplasmic immunoreactivity of LY6G6D was less frequent in mucinous carcinomas than in non-mucinous carcinomas CRC, (18–35%) (p < 0.05)." (PMID 35953834, 2022).
tumor (9 papers, 2016 to 2024). "As ERKs and JAK/STAT5 cascades have been implicated in immune evasion, we analyzed tumor-infiltrating immune cell subpopulations in relation to gene expression levels of LY6G6D, FUT4 and others key immune modulatory molecules." (PMID 30670049, 2019). "Therefore, we explored the association of LY6G6D with these tumor subtypes." (PMID 38791382, 2024). "Some of the marker genes of these clusters were associated with tumor progression, such as LYPD3 and LY6G6D." (PMID 36816947, 2023). "In a homogeneous population of LY6G6D positive cells, the LY6G6D/CD3 TcE induced potent tumor cell lysis and T cell activation which correlated with target density in the cell membrane." (PMID 36159851, 2022). "Basal expression of LY6G6D and infiltration of T cells was assessed by immunohistochemistry in fresh tumor tissue slices fixed in formalin." (PMID 36159851, 2022). "Ex vivo treatment of primary patient-derived CRC tumor slice cultures with the LY6G6D/CD3 TcE led to IFNγ secretion in LY6G6D positive tumor samples." (PMID 36159851, 2022). "In this study, we describe the identification of LY6G6D as a high tumor specific antigen in CRC, specifically in MSS tumors, confirming the same observations made by other groups." (PMID 36159851, 2022). "Similar tumor control was observed with donor B and C, (p < 0.01) demonstrating that the LY6G6D/CD3 TcE induces efficient tumor control in LY6G6D positive tumors." (PMID 36159851, 2022). "In fact, tumours with increased number of infiltrating leucocytes exhibited stronger LY6G6D expression in malignant cells." (PMID 30670049, 2019). "Our data identify LY6G6D antigen as a potential molecular target for human microsatellite stable tumours and provide evidences supporting that a combined targeting of MAPK and STAT5 signaling can improve the therapeutic response in this subtype." (PMID 30670049, 2019). "Although the interaction between mucinous CRC and the host immune system is unknown, one might hypothesize that the pathways regulating LY6G6D may differentially compromise anti-tumor immunity at the site of the primary tumor." (PMID 35953834, 2022). "Using public transcriptomic data, we identified LY6G6D as a CRC specific antigen within 11616 tumor samples from the Cancer Genome Atlas (TCGA), and 17588 normal samples from TCGA (normal adjacent, n=2150) and the Genotype-Tissue Expression project (GTEx, n=15438)." (PMID 36159851, 2022). "We interrogated whether the LY6G6D/CD3 TcE could activate tumor infiltrating lymphocytes (TILs) in precision cut tumor samples from CRC patients." (PMID 36159851, 2022). "Recently, our group discovered LY6G6D as a tumor-specific antigen of stable mismatch repair CRCs." (PMID 35953834, 2022). "Taken together, these results indicate that tumours bearing LY6G6D and CD15 might be targeted by this treatment strategy, particularly those from MSS CRC subgroup." (PMID 30670049, 2019). "Notably, phospho-Stat5 (P-STAT5) and LY6G6D positive staining displayed a direct correlation, so that, tumours with high levels of P-STAT5 and LY6G6D (LY6G6Dhi) were associated with a shorter patients survival rate." (PMID 30670049, 2019). "Notably, more than 80% of tumours exhibited LY6G6D staining, compared to 20% of normal tissues." (PMID 30670049, 2019). "Given the role of LY6G6D as a TAA, we studied the type of immune cells that were present in the tumor microenvironment when tumors displayed high expression of LY6G6D." (PMID 38791382, 2024). "To further demonstrate the relevance of LY6G6D, we performed a prevalence analysis in CRC samples by immunohistochemistry and confirmed that 27% of the samples express LY6G6D on tumor cells." (PMID 36159851, 2022). "In this report, we describe the identification of LY6G6D as a tumor selectively expressed antigen in CRC, and the generation of a LY6G6D/CD3 bi-specific antibody to potently redirect T cells into LY6G6D expressing CRC cells." (PMID 36159851, 2022).
tumor (continued). "A specific anti LY6G6D/CD3 T cell engager (TcE) was generated and demonstrated potent tumor cell killing and T cell activation in vitro." (PMID 36159851, 2022). "GPR56, LY6G6D/F and SLCO1B3 protein expression was significantly correlated with the proximal tumor location and with expression of mismatch repair genes." (PMID 26894861, 2016). "In line with this, when we explored the tumor microenvironment, we observed a negative correlation between LY6G6D with adaptative immune cells including effector CD8+ T cells." (PMID 38791382, 2024). "Next, we examined the tumor microenvironment for infiltration of LY6G6D + cells in mucinous and non-mucinous tumors." (PMID 35953834, 2022). "in a recent publication, the expression distribution of LY6G6D makes this target a rare tumor specific antigen with differential expression in CRC versus normal tissues, which allows the generation of a TcE with very restricted on-target/off-tumor toxicity." (PMID 36159851, 2022). "The abundance of LY6G6D expression was analyzed in tumor samples of a CRC TMA (n=41) and non-malignant colon tissue using clone 10C1." (PMID 36159851, 2022). "Since LY6G6D expression in tumors shows some level of heterogeneity, this finding implies that bystander killing of target negative cells in the tumor could increase the therapeutic effect of the TcE." (PMID 36159851, 2022). "However, we corroborate that the lytic synapse should govern the direct killing of LY6G6D-positive tumor cells, since these cells were not protected from killing by the triple blockade." (PMID 36159851, 2022). "Overall, we concluded that LY6G6D is expressed in a significant percentage of CRC samples and could be a good target for T-cell engager, with the aim of redirecting T cells into CRC tumors, induce T cell activation and subsequent tumor cell killing." (PMID 36159851, 2022). "Notably, we confirmed that LY6G6D expression levels were significantly higher in MSS than in MSI subset and tend to be significantly higher in chromosomal instability high (CIN-high) than in CIN-low tumours." (PMID 30670049, 2019). "Semi-quantitative protein analysis revealed that LY6G6D, but not CD15, was consistently higher in stages III and IV than in stages I and II of primary tumours." (PMID 30670049, 2019). "Accordingly, double immunofluorescence on paraffin embedded tumours revealed that CD4+ and FOXP3+ T cells (Treg) were positive for LY6G6D staining, whereas CD8+ T lymphocytes did not." (PMID 30670049, 2019).
cancer (6 papers, 2019 to 2024). A tumor composed of atypical neoplastic, often pleomorphic cells that invade other tissues. "Therefore, further investigation will be required to fully elucidate the mechanism by which LY6G6D promotes cancer progression." (PMID 30670049, 2019). "Momelotinib, an inhibitor of JAK1/JAK2, consistently abrogated the STAT5/LY6G6D axis in vitro, sensitizing MSS cancer cells with an intact JAK-STAT signaling, to efficiently respond to trametinib, a MEK inhibitor used in clinical setting." (PMID 30670049, 2019). "Our observations reveal that MMR proficient cancers characterized by less CD8+ T lymphocytes and low expression of PD-1/PD-L1 exhibit enhanced LY6G6D expression and STAT5 activation, implicating Ly6 genes as novel candidates for the development of new targeted therapies." (PMID 30670049, 2019).
adenocarcinoma (1 paper, 2022). A common cancer characterized by the presence of malignant glandular cells. "Because LY6G6D has not previously been associated with differences in histotype, we analyzed the global gene expression profiles of mucinous and classical adenocarcinomas in the COAD and READ TCGA databases." (PMID 35953834, 2022).
rectum (1 paper, 2024).
LY6G6D also shares sentences with these, for which no sentence is quoted: breast carcinoma (1 paper); immune diseases (1); infection (1); intestinal polyp (1); metastatic colorectal cancer (1); mucinous adenocarcinomas (1); rectal adenocarcinoma (1); rectal cancer (1); villous adenoma (1).